LEP (leptin)
Diseases named in the same sentence as LEP in open-access papers (continued):
Sharing a sentence is not in itself a finding about the gene and the disease.
Obesity (continued). "Furthermore, fenofibrate decreases leptin levels in animal models of obesity and decreases leptin secretion by adipose cell cultures from dyslipidemic but not from normolipidemic humans." (PMID 23781298, 2012). "The lack of LPL in beta cells of ob/ob mice could be due to the lack of leptin per se, or could be a consequence of obesity and/or the high levels of glucose, fatty acids and insulin in the blood." (PMID 23186339, 2012). "Our data do not support the hypothesis that obesity or T2DM influences 24-hour leptin rhythms in controlled laboratory conditions." (PMID 22623983, 2012). "Further studies of mechanisms mediating adipose stem cell hyperplasia and leptin signaling in obesity are warranted and may help identify novel anti-obesity target strategies." (PMID 23216800, 2012). "It is however, not clear as to what extent adipose tissue, particularly leptin contributes quantitatively to the elevated circulating levels of acute phase proteins and cytokines in obesity and whether there is a generalized or local state of inflammation." (PMID 22891684, 2012). "Moreover, children lacking leptin showed severe obesity, but when exogenous leptin was given, obesity decreased considerably." (PMID 23009606, 2012). "Leptin levels predict metabolic syndrome development independent of obesity." (PMID 22533665, 2012). "Moreover, recent evidence suggests that the neurobiology of leptin signaling in obesity appears to involve central leptin insufficiency, as opposed to the previously postulated notion of leptin resistance." (PMID 22518191, 2012). "Leptin is not a simple satiety signal to prevent obesity in times of energy excess." (PMID 23675258, 2012). "However, leptin is not an easy drug to administer, and the current treatment for obesity involves giving subcutaneous injections of the drug." (PMID 22013440, 2011). "This may be because of the differing degrees of obesity or due to a specific effect of the lack of leptin in the ob/ob mouse." (PMID 21731698, 2011). "Unexpectedly, the degree of obesity induced bythe post-weaning P diet was not exacerbated in offspring born to obese dams andplasma parameters were similar in both groups of leptin-resistant rats, excepthigher insulin and HOMA values and lower cholesterol level, in the PP than in the PCgroup." (PMID 21464991, 2011). "Notably, obesity in the F line is independent of leptin, the leptin receptor and other characterised single gene obesity mutations relating to central control of appetite or energy balance." (PMID 21915269, 2011). "However, our finding of reduced leptin gene expression in the epididymal fat of mice with long-standing obesity is not consistent with previous reports." (PMID 22051061, 2011). "Since, plasma leptin and its mRNA expression are synonymous with obesity and TG induced adipocyte hypertrophy, the results recorded herein are indicative of the mitigative nature of SRLE against HFD induced visceral adiposity, essentially by altered leptin gene expression in adipocytes." (PMID 21845103, 2011). "However, decoding its pulmonary impact is not an easy task, since the role of leptin cannot always be separated from obesity and the biology of adipose tissue." (PMID 21040518, 2010). "Recently, we examined if prolonged hyperleptinemia may induce resistance to natriuretic effect of leptin in the absence of obesity." (PMID 21286276, 2010). "Leptin increases in adult AC3−/− mice may reflect increased adipocyte size and obesity." (PMID 19750222, 2009). "While infants with PWS, have higher leptin levels than controls, suggesting a relative excess of fat to lean body mass, adults with PWS have leptin assessment corresponding to their degree of obesity (see Endocrine and Therapeutic Implications, GH treatment and the Prader-Willi syndrome (PWS))." (PMID 19878575, 2009).
Obesity (continued). "Under experimental conditions, intermittent hypoxia stimulates leptin production and a number of studies have demonstrated that serum leptin levels are elevated in OSA patients, independently of obesity despite some couldn't find that relationship when controlled for body fat." (PMID 18828917, 2008). "However, important central regulatory proteins such as the obesity gene leptin or PPAR-γ were not differentially expressed after 6 h exposure." (PMID 18681965, 2008). "This study aims to determine and compare the serum leptin concentrations of diabetic and non-diabetic patients with those in patients who have pre-diabetes and to correlate it with anthropometric measures of obesity." (PMID 17617917, 2007). "However, given the close correlation of leptin with indices of adipose tissue mass, no studies were able to investigate if leptin relates to those variables through obesity and/or hyperinsulinaemia, or independent of them." (PMID 16669997, 2006). "This is in accordance with the hypothesis that leptin may serve as an anti-starvation as opposed to an anti-obesity signal." (PMID 16942616, 2006). "Besides, the Glu27 polymorphism was associated with rheumatoid arthritis, coronary events in elderly patients, elevated leptin and triglycerides levels, but not with hypertension, blood pressure and heart size, obesity and DM." (PMID 16573811, 2006). "Our data suggest that defects in innate immune function observed in genetically obese animals are not mimicked by dietary obesity, and may more likely reflect the gross abnormality in leptin function of these models." (PMID 15813957, 2005). "Consequently, the link between obesity and AD may not be explained concerning the leptin plasma level." (PMID 40498212, 2025). "Importantly, these findings could also be influenced by the obesity stage in ob/ob mice rather than solely by the absence of circulating leptin." (PMID 40714221, 2025). "Obesity may also influence breast cancer development through various other mechanisms, including activation of the PI3K/Akt/mTOR signaling pathway, upregulation of leptin, downregulation of adiponectin, increased insulin-like growth factor signaling, and elevated proinflammatory cytokine production." (PMID 41227211, 2025). "Central administration of the TLR4 inhibitor TAK242 enhanced leptin-induced suppression of food intake in rats with diet-induced obesity, but did not exert additive effects in RYGB-treated animals, indicating that RYGB may exert its benefits through this mechanism." (PMID 40500780, 2025). "Indeed, individuals with leptin-resistance due to mid-life obesity are unlikely to see any benefit, whereas those with low circulating leptin levels may be highly responsive to leptin replacement." (PMID 41462981, 2025). "Obesity is characterised by a chronic low-grade inflammatory state and many biomarkers categorised as either metabolic (e.g., cholesterol, insulin resistance) or inflammatory (e.g., CRP, leptin, adiponectin) may reflect overlapping pathophysiological pathways linked to adiposity." (PMID 41050371, 2025). "However, leptin excess secretion due to obesity can have a negative effect on reproduction." (PMID 40566611, 2025). "Second, comparing leptin levels and their correlations in well-nourished populations—both in physiological pregnancies and those complicated by conditions such as gestational diabetes, hypertension, IUGR, and obesity—could enhance our understanding of how malnutrition may affect leptin’s function." (PMID 39940373, 2025). "Importantly, adipocyte hypertrophy was associated with lower adiponectin, omentin, and visfatin mRNA expression in both subcutaneous and visceral adipose tissues in individuals with obesity, and with higher visceral LEP mRNA expression in individuals without obesity." (PMID 41271970, 2025).
Obesity (continued). "Moreover, RESILIENT project will offer a protocol for the study in vivo and ex vivo of leptin sensitivity that can be reproduced for evaluating metabolic and cognitive effects of anti-obesity medications, i.e. not just glucagon like peptide 1 and setmelanotide, but also amylin." (PMID 40607230, 2025). "Additionally, obesity may increase the levels of soluble LEPR, which limits leptin bioavailability." (PMID 39317805, 2024). "Therefore, we analysed the transcriptome of GCs collected from antral follicles isolated from genetically obese db/db and ob/ob mice to pinpoint the effects of ObRb (canonical) and non-ObRb (noncanonical)-mediated leptin signalling on GC function regulation during obesity." (PMID 38580672, 2024). "Three groups—no obesity (33 cases), obesity (26 cases), and overweight (41 cases)—were compared according to the family history of the 100 selected children, and we examined whether LEPR and LEP gene polymorphisms and 51 nt and 31 nt methylation were related." (PMID 39594868, 2024). "Interestingly, in vitro leptin treatment did not alter the expression of Ob-Rb, the long isoform of the leptin receptor, in ASCs from obese mice, suggesting stable receptor expression despite the conditions of obesity." (PMID 39065712, 2024). "However, administration of exogenous leptin in people with obesity has not been effective." (PMID 38206766, 2024). "Taken together, our study reveals that secondary sarcopenia of RA females may be an imbalance of RA‐related, but not obesity‐related, increase in adipokine production; additionally, the reduced leptin/adiponectin ratio could be a better indicator in monitoring sarcopenia in non‐obese RA females." (PMID 38602220, 2024). "The name leptin was derived from leptos, the Greek root for thin, because leptin was initially considered to be a signal from adipose tissue to the brain; rising levels of leptin acted through a negative feedback mechanism to limit obesity by reducing food intake and increasing energy expenditure." (PMID 38165042, 2024). "Therefore, leptin antagonism therapy is not expected to help in reducing BP, whereas it might even worsen obesity." (PMID 38186879, 2024). "In addition, the capacity of probiotics to regulate HDL-cholesterol, LDL-cholesterol, adiponectin, leptin, and TNF-α, as well as regulate lipid metabolism and reduce inflammation, was demonstrated in a systematic review studying the effects of probiotics in children with obesity." (PMID 39596385, 2024). "Due to this increased work of breathing, patients with obesity need a higher central respiratory drive to maintain levels of oxygen and carbon dioxide, but patients with OHS do not maintain eucapnia due to a blunted central respiratory drive, which may be due to leptin resistance." (PMID 39274213, 2024). "The observed decrease in leptin levels after IAP administration suggests that IAP may not only mitigate inflammation but could also potentially contribute to weight management in the context of obesity." (PMID 38255781, 2024). "Consequently, the increased leptin and decreased adiponectin levels in HFD-fed mice and their reversal by euiin-tang suggest that modulating adipokines may also be crucial for treating obesity and OIA." (PMID 39065704, 2024). "Leptin could be an important predictor of insulin resistance independent of the degree of obesity." (PMID 37049561, 2023). "In the absence of leptin signaling in obesity, other cytokine signals may be compensatory." (PMID 37276236, 2023). "However, treatment with leptin in obesity did not produce the expected effects." (PMID 38068822, 2023). "CRP in chronic inflammatory conditions of obesity can also damage the function of BBB and increase BBB permeability, resulting in reactive glial proliferation and affecting central nervous system function, which may be a major factor of central leptin resistance in chronic inflammation." (PMID 37660067, 2023).
Obesity (continued). "Also, obesity is related to a pro-oxidative status with reactive oxygen species (ROS) generation, increased production of NADPH oxidase (NOX), decreased expression of antioxidant enzymes and dysregulated production of adipokines, such as adiponectin, and leptin." (PMID 37529617, 2023). "However, this does not exclude the possibility that leptin in combination with a yet unknown cofactor might have the capacity to regulate body weight in common obesity." (PMID 37661748, 2023). "Thus, they develop leptin resistance in the absence of obesity." (PMID 38031726, 2023). "Indeed, PTP1B-knockout mice exhibited a phenotype ascribable to both enhanced leptin and insulin signaling, characterized by improved sensitivity of target tissues to insulin and resistance to diet-induced obesity, without any alterations in growth or viability." (PMID 37298571, 2023). "Furthermore, after incorporating all variables through a multivariate logistic regression, the study reported a significantly higher chance of SCFE diagnosis based solely on leptin elevation, regardless of obesity status, sex, and race (OD = 4.9; 95%CI:1.31–18.48; p < 0.02)." (PMID 37238326, 2023). "However, leptin does not affect the release of Il-22 from gut immune cells, and the absence of Il-22 in portal vein and systemic plasma samples of Sham rats is most likely explained by their obesity." (PMID 36992680, 2023). "However, to the best of our knowledge, whether leptin can exert these protective effects in the offspring of rats with diet-induced obesity, exposed or not to an obesogenic diet during lactation, has not been studied so far." (PMID 36771278, 2023). "Therefore, leptin could have negative, positive or neutral effects on bone in obesity, depending on the balance of these actions." (PMID 36173650, 2022). "In one study, a positive relationship between leptin levels and BMD was found to be greater in menopausal women with obesity than in the rest of the studied patients, which could be due to a state of resistance to leptin in the central nervous system in patients with obesity." (PMID 35955431, 2022). "However, no clear additive effects of obesity on leptin levels in asthma were detected." (PMID 35807067, 2022). "However, obesity’s contribution to IH-induced cardiac dysfunction, independent of leptin signaling, remains unclear." (PMID 36160851, 2022). "Therefore, the observed increase in fasting leptin levels in this study is promising, considering the physiological effects of this hormone on the control of food intake and energy homeostasis in individuals not diagnosed with obesity." (PMID 34928408, 2022). "This insight into leptin and insulin signaling in HRA neurons led them to hypothesize that hyperleptinemia in obese-induced mice might lead to an imbalance between leptin and insulin signaling in HRA neurons and, consequently, affect the regulation of glucose homeostasis in obesity." (PMID 36290695, 2022). "Leptin plays a role in T-cell thymus development, naive CD4+ T-cell proliferation, and Ki67 expression in CD4+ T cells, and HIV patients with higher leptin levels have better immune reconstitution, suggesting that obesity may play a protective role in immune reconstitution in HIV patients." (PMID 36584083, 2022). "Therefore, leptin and its receptor have shown mixed results, with several studies demonstrating positive correlation and some showing a lack of correlation between the genes and obesity." (PMID 36551995, 2022). "During the pre-weaning suckling period, and consistent with the previously reported anti-obesity effect of celastrol, animals from both celastrol and Lep+Cel groups showed a decrease in body weight compared to control animals, while treatment with leptin did not affect weight gain." (PMID 35684076, 2022).
Obesity (continued). "However, the contribution of other key adipokines and cytokines in this obesity-associated CSC/EMT circuit must be further examined, as preliminary studies indicate that the leptin-adiponectin ratio imbalances do not fully account for all of the observed effects of diet-induced obesity on TNBC." (PMID 36531496, 2022). "In our previous study with ZDF rats, we found that intact leptin signaling was necessary for the full effect of palm-PrRP31 on metabolic parameters such as BW-lowering or glucose tolerance; therefore, its antidiabetic and anti-obesity effects were not realized." (PMID 35589696, 2022). "Previous studies have suggested leptin might help in the increased insulin sensitivity as well as improved insulin resistance while such benefits are absent in diabetic patients with obesity due to leptin resistance." (PMID 34996484, 2022). "Finally, high leptin expression was shown to mediate MAPK/ERK signaling pathway activation, leading to abnormal expression of key cartilage genes and proteins in offspring male mice from the maternal obesity group, resulting in chondrocyte damage and reduced collagen II expressions." (PMID 35327669, 2022). "Therefore, in terms of metabolic programming results, maternal Se supplementation leads to high insulin non-operative secretion resulting in obesity, anabolism, inflammation, and low leptin levels, all parameters similar to those found in a T2DM process in pups." (PMID 35204276, 2022). "Leptin was shown to be inversely correlated with both FEV1, FVC/FEV1 ratio, and FEV1/FVC ratio, which may suggest that nonatopic inflammation (including not only leptin, but also other adipokines such as adiponectin) increase the severity of asthma by obesity-dependent and independent mechanisms." (PMID 36613991, 2022). "Thus, leptin plays a central role in reproduction and may be one component explaining the negative effect of obesity on IVF outcome." (PMID 35922472, 2022). "However, leptin is not the only factor at play in obesity tumour growth, highlighted by recent work in pancreatic adenocarcinoma mouse models demonstrating accelerated tumorigenesis in obese mice deficient in leptin signalling with the possible involvement of cholecystokinin." (PMID 36038791, 2022). "Therefore, the hypothesis was that leptin would provide an effective anti-obesity therapy, but this link was not confirmed by robust scientific evidence." (PMID 34173157, 2021). "Also in this study, leptin and other adipokines related to obesity were not measured." (PMID 34742317, 2021). "However, both endo- and exogenous high leptin levels do not act against developing obesity." (PMID 35056501, 2021). "Moreover, severe Trp restriction decreases the plasma leptin and ghrelin concentrations and increases the plasma GLP-1 and PYY concentrations, which leads to decreased feed intake and body weight, while moderate Trp restriction increases energy expenditure in obesity-prone rats." (PMID 34284827, 2021). "In patients with knee OA and BMI ≥ 30 kg/m2 serum levels of leptin (39.546 ± 12.918 ng/mL) were significantly higher as compared with the control group, which was comprised of individuals with different BMIs, including cases with obesity but without OA (15.832 ± 16.531 ng/mL, p < 0.05)." (PMID 34440223, 2021). "However, there is no systematic review of acupuncture for the treatment of leptin resistance in obesity, and this is the first randomized controlled trial using meta-analysis to explore the effects of acupuncture interventions in obese leptin resistant patients." (PMID 34260523, 2021). "Thus, individuals with midlife obesity and leptin resistance may not respond, whereas treatment with leptin may offer significant benefit to patients with low circulating leptin levels." (PMID 33440796, 2021). "Furthermore, this effect may be mediated by leptin, which inhibits NPY and is elevated in obesity." (PMID 33670342, 2021).